GLDN (gliomedin)
Description:
Ligand for NRCAM and NFASC/neurofascin that plays a role in the formation and maintenance of the nodes of Ranvier on myelinated axons. Mediates interaction between Schwann cell microvilli and axons via its interactions with NRCAM and NFASC. Nodes of Ranvier contain clustered sodium channels that are crucial for the saltatory propagation of action potentials along myelinated axons. During development, nodes of Ranvier are formed by the fusion of two heminodes. Required for normal clustering of sodium channels at heminodes; not required for the formation of mature nodes with normal sodium channel clusters. Required, together with NRCAM, for maintaining NFASC and sodium channel clusters at mature nodes of Ranvier.
Synonyms: COLM; CRG-L2; CLOM; colmedin; UNC-122; CRGL2; LCCS11; UNC-112
Tractability: Antibody: UniProt places it where antibodies can reach, with high confidence; UniProt predicts a signal peptide or a membrane-spanning region; its Gene Ontology location is reachable by antibodies, with medium confidence; the Human Protein Atlas places it where antibodies can reach.
Safety:
Unwanted effects reported when the protein is acted on. In parentheses: how it was acted on, where the effect was seen, and who reports it.
bone density loss (source: ClinPGx)
odds of vasomotor symptoms (source: ClinPGx)
odds of vasomotor symptoms (VMSs) (source: ClinPGx)
Gene: Protein-coding gene on chromosome 15 (51,341,611 to 51,408,005, forward strand). Ensembl gene ENSG00000186417.
Subcellular location: Cell membrane; Cell projection, axon; Secreted (Gliomedin shedded ectodomain); Secreted, extracellular space, extracellular matrix
Subcellular location (Human Protein Atlas): Plasma membrane; Vesicles; Predicted to be secreted
Gene Ontology:
Molecular function: protein binding involved in heterotypic cell-cell adhesion
Biological process: signal transduction; heterotypic cell-cell adhesion
Cellular component: cell surface; plasma membrane; extracellular region; non-collagenous component of interstitial matrix; axon
Genetic constraint (gnomAD): Loss-of-function variants: 43 observed, 51.43 expected, observed/expected ratio (o/e) 0.84, 90% interval 0.65 to 1.08. The synonymous counts are far from expectation, so gnomAD's model fits this gene poorly and the ratio says little. Missense variants: 752 observed, 663.78 expected, observed/expected ratio (o/e) 1.13, 90% interval 1.07 to 1.2. Synonymous variants: 320 observed, 254.24 expected, observed/expected ratio (o/e) 1.26, 90% interval 1.15 to 1.38.
Gene-disease validity (ClinGen):
ClinGen rates the evidence that GLDN causes each of these diseases.
lethal congenital contracture syndrome 11 (autosomal recessive): Definitive. Any lethal congenital contracture syndrome in which the cause of the disease is a mutation in the GLDN gene.
Homologues: Orthologues: chimpanzee GLDN (99% identical), macaque GLDN (97% identical), pig GLDN (89% identical), dog GLDN (88% identical), rabbit GLDN (87% identical), mouse Gldn (86% identical), rat Gldn (85% identical), guinea pig GLDN (58% identical), tropical clawed frog gldn (56% identical), zebrafish gldn (42% identical). Paralogues in human: OLFM1 (19% identical), OLFML2A (18% identical), OLFML2B (18% identical), OLFM2 (17% identical), OLFM3 (17% identical), MYOC (15% identical), OLFM4 (15% identical), OLFML3 (13% identical), OLFML1 (11% identical).
Diseases named in the same sentence as GLDN in open-access papers:
GLDN is named in the same sentence as 35 diseases in open-access papers, as found by Europe PMC text mining. Sharing a sentence is not in itself a finding about the gene and the disease. The quoted sentences say what the papers report.
bladder cancer (2 papers, 2020 to 2022). "In the GWAS and gene-wise analysis, the gliomedin gene satisfied both suggestive association levels of 10−5 in the GWAS and 10−4 in the gene-wise analysis for male bladder cancer." (PMID 35328002, 2022). "Under these conditions, the gliomedin gene was detected in this study by GWAS and gene-wise analysis as a gene that may be associated with the development of bladder cancer in males." (PMID 35328002, 2022). "As GWAS suggested a relationship between the gliomedin gene and the development of bladder cancer in men, further studies are required." (PMID 35328002, 2022). "The expression of the gliomedin protein in the nucleus of bladder cancer cells decreased in cancers with a tendency to infiltrate and those with strong cell atypia." (PMID 35328002, 2022). "In addition, the expression of the gliomedin protein in the nucleus of bladder cancer cells was lower in cancers with a tendency to infiltrate and those with strong cell atypia." (PMID 35328002, 2022). "As the expression of the gliomedin protein in the nucleus of cancer cells is decreased in bladder cancer with strong nuclear atypia and infiltration tendency, it is speculated that gliomedin may act as a tumor suppressor factor in bladder cancer." (PMID 35328002, 2022). "It is hypothesized that gliomedin is involved in the development of bladder cancer." (PMID 35328002, 2022). "Thus, it is hypothesized that gliomedin is also involved in the development of bladder cancer by a mechanism similar to that of olfactomedin 4 in innate immunity and oncogenesis in a certain environment." (PMID 35328002, 2022).
chronic inflammatory demyelinating polyneuropathy (2 papers, 2015 to 2025). "Antibodies against contactin-1, neurofascin and gliomedin have been reported to be present in 2–10% of patients with chronic inflammatory demyelinating polyneuropathy (CIDP) and are supposed to be associated with a typical clinical phenotype of acute onset severe sensorimotor neuropathy and tremor." (PMID 26218529, 2015). "Auto antibodies to GLDN have been detected in other chronic demyelinating conditions such as multiple sclerosis (MS) involving the CNS and in particular chronic inflammatory demyelinating polyradiculoneuropathy involving the peripheral nervous system." (PMID 41146907, 2025).
melanoma (2 papers, 2020 to 2024). A malignant, usually aggressive tumor composed of atypical, neoplastic melanocytes. "Further, both genes with increased expression in intracranial metastases (PMP2 and GLDN) have known associations with melanoma cell invasion and mutation." (PMID 38671536, 2024). "GLDN is a potential prognostic biomarker that predicts the overall survival (OS) of patients with colorectal cancer and melanoma patients that may benefit from immunotherapy." (PMID 32644941, 2020).
acute inflammatory demyelinating polyneuropathy (1 paper, 2013). "Nevertheless, antibodies to Gliomedin and Contactin-1 are mostly associated with the demyelinating form of GBS, acute inflammatory demyelinating polyneuropathy (AIDP), and with CIDP." (PMID 24194699, 2013).
Anxiety (1 paper, 2025). Intense feelings of nervousness, tension, or panic often arise in response to interpersonal stresses. "In subjects with other non-neurologic symptoms, that is no fatigue, but depression and/or anxiety, and insomnia all had high gliomedin, a peripheral nerve target, normal C5a and a mix of high and normal TGF-β1." (PMID 41146907, 2025).
arthrogryposis multiplex congenita (1 paper, 2022). Arthrogryposis multiplex congenita (AMC) is a group of disorders characterized by congenital limb contractures. "Lethal congenital contracture syndrome 11 (LCCS11) is a form of arthrogryposis multiplex congenita (AMC) which is associated with mutations in the gliomedin gene (GLDN) and has been known to be severely life-shortening, mainly due to respiratory insufficiency." (PMID 35740734, 2022).
cognitive deficits (1 paper, 2025). "Intellectual disability was universally present in individuals with variants in ZC4H2 (5/5), DYNC1H1 (4/4), TOR1A (2/2), KAT6B (1/1), GLDN (1/1), and GPC3 (1/1), signifying a strong association between these genes and cognitive deficits." (PMID 40443119, 2025).
congenital myopathy (1 paper, 2020). "In contrast to this GLDN‐associated lethal congenital arthrogryposis and congenital myopathy Compton‐North, resulting from homozygous CNTN1 variants, are only associated with a severe phenotype, leading to death early in life, mostly after the first days, almost independent of the type of variant." (PMID 32779773, 2020).
Respiratory insufficiency (1 paper, 2022). "In this case report, we present a young adult who developed severe progressive respiratory insufficiency as a teenager due to diaphragmatic hypomotility and was diagnosed with LCCS11 following the discovery of compound heterozygous pathogenic variants in GLDN." (PMID 35740734, 2022).
cancer (4 papers, 2020 to 2024). A tumor composed of atypical neoplastic, often pleomorphic cells that invade other tissues. "The expression of gliomedin mRNA and protein is found in the nuclei of many types of cancer cells, including urothelial cancer." (PMID 35328002, 2022). "Using the ChIP Seq bam files, we visualized the exact genomic location of DVL-1 binding (blue peak) at various cancer-associated genes not previously designated as Wnt target genes such as TRIO, COL5A1, EXD3, OR4A47, GLDN, and EFCAB6 compared to IgG control (red peak) using IGV." (PMID 34659647, 2021).
tumor (4 papers, 2014 to 2022). "We also found that the expression of these 5 genes, namely, ANGPT2, EMCN, GLDN, USHBP1 and ZNF532, was significantly upregulated in HCC tumor tissues compared to the adjacent normal liver tissues in the TCGA and ICGC datasets." (PMID 32644941, 2020). "The expression of ANGPT2, GLDN, and ZNF532 was significantly higher in the 268 HCC tumor tissues of the GSE25097 dataset compared to the 243 non-tumor liver tissue samples (p < 0.001)." (PMID 32644941, 2020).
peripheral neuropathies (1 paper, 2019). "Biallelic variants in gliomedin (GLDN) and CNTNAP1 encoding essential components of the nodes of Ranvier and paranodes, respectively, lead to inherited nodo-paranodopathies, a distinct disease entity among peripheral neuropathies." (PMID 31501903, 2019).
GLDN also shares sentences with these, for which no sentence is quoted: gastric cancer (2 papers); lung carcinoma (2); Anosmia (1); asthma (1); breast carcinoma (1); cellulitis (1); cervical cancer (1); colon cancer (1); colorectal cancer (1); depression (1); esophageal cancer (1); head and neck cancer (1); hepatocellular carcinoma (1); insomnia (1); Intellectual disability (1); kidney cancer (1); Klebsiella pneumonia (1); lethal congenital contracture syndrome 11 (1); leukemia (1); liver cancer (1); lung adenocarcinoma (1); lymphoma (1); multiple sclerosis (1).